SMOC1 (SPARC related modular calcium binding 1)
Diseases named in the same sentence as SMOC1 in open-access papers (continued):
Sharing a sentence is not in itself a finding about the gene and the disease.
Obesity (4 papers, 2019 to 2023). Accumulation of substantial excess body fat. "Second, using bidirectional MR), we sought to determine whether blood levels of SMOC1 were causally influenced by NAFLD, obesity or glycemic traits and if SMOC1 could be causally implicated in the etiology of metabolic traits and metabolic diseases such as NAFLD and T2D." (PMID 34959760, 2021). "In people with insulin resistance and obesity, SMOC1 blood levels were statistically significantly lower than in people without these diseases." (PMID 34959760, 2021). "By comparing regulators that were identified for lean, obese, and merged islet expression data, Cck, C1ql3, Serpina7, Creld2, Svop, Smoc1, Tgfβ3, and Serpini1 were identified to affect islet function in obesity." (PMID 31300714, 2019). "Although lower SMOC1 levels in the blood have been demonstrated in the setting of insulin resistance and obesity in humans, the causal role of SMOC1 on the etiology of T2D and obesity in humans has not been investigated." (PMID 34959760, 2021). "Altogether, we found little evidence for a causal role of NAFLD, T2D, obesity and glycemic traits in the regulation of SMOC1 blood levels." (PMID 34959760, 2021).
astrocytomas (3 papers, 2004 to 2021). "A restricted set of tumor-associated genes was identified for each grade that included genes not previously associated with astrocytomas (e.g. VCAM1, SMOC1, and thymidylate synthetase), with a high percentage of cell surface genes." (PMID 15265232, 2004).
oligodendroglioma (3 papers, 2021). A well-differentiated (WHO grade II), diffusely infiltrating neuroglial tumor, typically located in the cerebral hemispheres. "The expression of SMOC1 was increased in oligodendroglioma and astrocytic tumors." (PMID 34869577, 2021).
adenoma (2 papers, 2018 to 2024). A neoplasm arising from the epithelium. "In this study, we showed that reduced expression of SMOC1 is associated with progression of colorectal tumors, including TSAs and conventional adenomas." (PMID 38429655, 2024). "The results summarized above suggest that SMOC1 methylation is associated with malignant progression of colorectal tumors, including TSAs and conventional adenomas." (PMID 29435136, 2018). "SMOC1 methylation-positive adenomas and cancers were associated with frequent KRAS mutation and a lack of MLH1 methylation." (PMID 29435136, 2018). "Our results suggest that reduced expression of SMOC1 is associated with progression of TSAs and conventional adenomas and that SMOC1 expression may be a biomarker for diagnosis of serrated lesions and risk prediction in colorectal tumors." (PMID 38429655, 2024). "SMOC1 expression could thus be a diagnostic marker of serrated lesions, and SMOC1 methylation could play a role in neoplastic pathways in TSAs and conventional adenomas." (PMID 29435136, 2018). "A positive correlation between SMOC1 expression and flat morphology was also observed in advanced adenomas and early invasive cancers." (PMID 38429655, 2024). "SMOC1 was abundantly expressed in normal colon and SSLs while it was significantly downregulated in TSAs, advanced adenomas and cancers." (PMID 38429655, 2024). "To that end, we performed an immunohistochemical analysis of SMOC1 in a series of colorectal lesions, including serrated lesions, conventional adenomas and CRCs." (PMID 38429655, 2024). "Analysis of colorectal lesions (n = 847) revealed that SMOC1 is frequently methylated in TSAs, high-grade adenomas and CRCs." (PMID 29435136, 2018). "Among the adenoma specimens with cancer (n = 23), elevated SMOC1 methylation was found in 6 adenomas and 10 samples of cancer tissue." (PMID 29435136, 2018). "Epigenetic silencing of SMOC1 may be associated with the development of KRAS mutant, CIMP-low and MSS CRCs derived from TSAs or conventional adenomas." (PMID 29435136, 2018). "Notably, high SMOC1 methylation was more prevalent in high-grade adenomas than low-grade adenomas." (PMID 29435136, 2018). "In addition to TSAs, SMOC1 was frequently methylated in high-grade adenomas and CRCs, suggesting SMOC1 may play a common tumor suppressor role during colorectal tumorigenesis." (PMID 29435136, 2018). "We observed that SMOC1 (SPARC-related molecular calcium-binding 1) was frequently methylated and silenced in TSAs as well as in advanced adenomas and CRCs." (PMID 38429655, 2024).
atherosclerosis (2 papers, 2022 to 2025). A disease characterized by the build-up of fatty material and calcium deposition in the arterial wall resulting in partial or complete occlusion of the arterial lumen. "These proteins, along with modular calcium-binding protein 1 (SMOC1), which promotes platelet responsiveness to thrombin, PDGF, which promotes the calcification of vascular smooth muscle cells in atherosclerosis, and neutrophil-derived S100A8/A9, create a proinflammatory, proatherosclerotic milieu." (PMID 40829182, 2025).
brain cancer (2 papers, 2021 to 2024). A primary or metastatic malignant neoplasm affecting the brain. "While elevated SMOC1 expression and protein levels in brain cancer compared to normal brain, was previously reported, differential SMOC1 isoform expression has not." (PMID 38287261, 2024).
cerebral amyloid angiopathy (2 papers, 2024). "SMOC1 is also significantly enriched in cerebral amyloid angiopathy (CAA) in comparison to blood vessels without CAA, suggesting that the SMOC1 association with amyloid beta (Aβ) is not limited to plaques." (PMID 39574902, 2024).
colon cancer (2 papers, 2021 to 2024). "They found that SMOC1 expression is associated with a better prognosis in colon cancer patients, suggesting a protective role for SMOC1." (PMID 38429655, 2024). "One in silico study analyzed the expression and prognostic data of long noncoding RNAs, microRNAs, and mRNAs in the colon cancer dataset from the TCGA database and identified five mRNAs, including SMOC1, as potential prognostic biomarkers for colon cancer." (PMID 34869577, 2021).
colorectal tumors (2 papers, 2018 to 2024). "We showed here that SMOC1 methylation is associated with transcriptional silencing in both primary and cultured colorectal tumor cells." (PMID 29435136, 2018). "When we analyzed a series of invasive colorectal tumors (n = 374), we again found that elevated SMOC1 methylation was associated with KRAS mutation and CIMP-low." (PMID 29435136, 2018). "We also examined the association between SMOC1 methylation and the clinicopathological features in a large cohort of patients with non-invasive colorectal tumors (n = 473)." (PMID 29435136, 2018). "Our findings suggest that expression of SMOC1 may be a diagnostic marker of serrated lesions as well as a predictive marker of colorectal tumors at high risk of developing into cancer." (PMID 38429655, 2024). "Although there have been few studies focused on SMOC1 in colorectal tumors, recent multi-omics analyses suggest the involvement of SMOC1 in CRCs." (PMID 38429655, 2024). "SMOC1 expression was analyzed immunohistochemically in a series of colorectal tumors (n = 199) and adjacent normal colonic tissues (n = 112)." (PMID 38429655, 2024). "To investigate the function of SMOC1 in colorectal tumors, we transfected CRC cells with a SMOC1 expression vector or empty vector and confirmed the protein expression with western blotting." (PMID 29435136, 2018). "In the present study, we aimed to further characterize SMOC1 expression in colorectal tumors." (PMID 38429655, 2024). "However, the function of SMOC1 remains largely unknown, and further study will be necessary to clarify the biological significance of SMOC1 methylation in colorectal tumors." (PMID 29435136, 2018).
diabetes (2 papers, 2024 to 2025). "In this study, we aimed to decipher the effect of HIIT and combined probiotic consumption on the gene expression of SMOC-1 hepatokines, blood glucose (BG), and IR in male rats with induced diabetes." (PMID 41194976, 2025). "In individuals with diabetes or excessive weight, SMOC-1 levels are usually reduced." (PMID 41194976, 2025).
gastric cancer (2 papers, 2018 to 2025). A primary or metastatic malignant neoplasm involving the stomach. "Because all CRC cell lines only minimally expressed SMOC1, we analyzed SMOC1 expression in a series of gastric cancer (GC) cell lines." (PMID 29435136, 2018).
Insulin resistance (2 papers, 2021 to 2025). Increased resistance towards insulin, that is, diminished effectiveness of insulin in reducing blood glucose levels. "These events highlight the importance of SMOC-1 in reducing insulin resistance (IR) and improving glucose tolerance, potentially through enhanced insulin-regulated glucose transporter (GLUT4) activity." (PMID 41194976, 2025).
low grade glioma (2 papers, 2021 to 2024). A grade I or grade II glioma arising from the central nervous system. "Furthermore, LinkedOmics was used to identify the genes coexpressed with SMOC1 and to perform Kyoto Encyclopedia of Genes and Genomes pathways and Gene Ontology analysis in low-grade glioma (LGG)." (PMID 34869577, 2021).
type 2 diabetes (2 papers, 2021 to 2022). "A recent study indicated that SMOC1 is a thrombin-activating protein that makes a significant contribution to the pathophysiological changes in platelet function associated with type 2 diabetes." (PMID 34959760, 2021). "Rather, circulating levels of SMOC1 were found to increase in subjects with type 2 diabetes in parallel with platelet hyperactivity to thrombin." (PMID 35626753, 2022).
Waardenburg Anophthalmia syndrome (2 papers, 2018 to 2024). "SMOC1 is also essential for ocular and limb development in humans and mice, and SMOC1 mutations were found to cause Waardenburg Anophthalmia syndrome." (PMID 38429655, 2024).
brain glioma (1 paper, 2021). A malignant glioma that involves the brain. "Survival analyzes from PrognoScan and GEPIA2 showed that the expression level of SMOC1 was correlated with the prognosis of brain glioma (LGG) and LUAD patients." (PMID 34869577, 2021).
colorectal adenoma (1 paper, 2018). An adenoma that arises from the colon or rectum. "We also found that SMOC1 methylation was frequently elevated in colorectal adenomas and cancers." (PMID 29435136, 2018).
dementia (1 paper, 2025). Loss of intellectual abilities interfering with an individual's social and occupational functions. "For instance, higher expression of WNT9A has been negatively correlated with cognitive performance in patients with dementia, and elevated SMOC1 concentrations were detected 30 years before the onset of Alzheimer's symptoms." (PMID 39812213, 2025).
Down syndrome (1 paper, 2023). "Indeed, SMOC1 and NTN1 were recently identified among the most highly-enriched proteins in amyloid plaques in early-onset AD and individuals with Down syndrome and AD41." (PMID 37414805, 2023).
dwarfism (1 paper, 2021). "Because we observed dwarfism and shortened long bones in Smoc1 and Smoc2 DKO mice, we investigated the roles of Smoc1 and Smoc2 in endochondral bone formation." (PMID 34667264, 2021).
hepatocellular carcinoma (1 paper, 2007). A malignant tumor that arises from hepatocytes. "Role of the other basement membrane proteins like agrin, collagen IV, laminin and fibronectin in liver cirrhosis and hepatocellular carcinoma has been studied but no report is available on the functional attributes of Smoc-1 in liver." (PMID 18042303, 2007). "Owing to its conservation in human and non-human systems, the fate of Smoc-1 gene may be studied in human liver cirrhosis, hepatocellular carcinoma and other liver infections to highlight its clinical aspects." (PMID 18042303, 2007). "However, since Smoc-1 is conserved across the species, it may not be inappropriate to study the expression of this gene in human hepatocellular carcinoma to ascertain its possible up- or down regulation." (PMID 18042303, 2007).
melanoma (1 paper, 2021). A malignant, usually aggressive tumor composed of atypical, neoplastic melanocytes. "Meanwhile, lower expression of SMOC1 was observed in melanoma, breast, colorectal, gastric, prostate, and other cancers." (PMID 34869577, 2021).
Myocardial fibrosis (1 paper, 2019). "SPARC-related modular calcium binding 1 (SMOC1) silencing can suppress myocardial fibrosis of mouse myocardial fibroblasts via regulation of the bone morphogenetic protein 2 (BMP2)/Smad signaling pathway." (PMID 32038243, 2019).
myocardial infarction (1 paper, 2025). Gross necrosis of the myocardium, as a result of interruption of the blood supply to the area, as in coronary thrombosis. "In our study, PLHIV with faster age advancement, and having either myocardial infarction or T2DM, showed higher levels of SMOC1 and WNT9A, indicating the involvement of these two proteins in age‐related processes in PLHIV." (PMID 39812213, 2025).
non-alcoholic fatty liver disease (1 paper, 2021). "Recently, Sparc-related modular calcium-binding protein 1 (SMOC1) was identified as glucose-responsive hepatokine that is dysregulated in the setting of non-alcoholic fatty liver disease (NAFLD)." (PMID 34959760, 2021).
osteonecrosis (1 paper, 2024). A none disease characterized by death of bone tissue due to a lack of blood supply. "This comprehensive MR study identifies 71 plasma proteins associated with osteonecrosis, with HEBP1, ITIH1, SMOC1, and CREG1 showing potential as biomarkers of osteonecrosis." (PMID 39119575, 2024). "Additionally, we also found a suggestive association of inter-alpha trypsin inhibitor heavy chain 1 (ITIH1), secreted modular calcium-binding protein 1 (SMOC1), and cellular repressor of E1A-stimulated genes 1 (CREG1) proteins with osteonecrosis risk." (PMID 39119575, 2024). "These experimental and population studies imply that SMOC1 may be a potential target for osteonecrosis therapy." (PMID 39119575, 2024). "The association between SMOC1 and osteonecrosis risk has not been investigated." (PMID 39119575, 2024).
osteoporosis (1 paper, 2020). A condition of reduced bone mass, with decreased cortical thickness and a decrease in the number and size of the trabeculae of cancellous bone (but normal chemical composition), resulting in increased fracture incidence. "Our results are consistent with results from genome-wide association studies of bone mineral density and osteoporosis, where SMOC1 has been identified as the candidate gene underlying the signal on chromosome 14." (PMID 33210602, 2020).
tumor (20 papers, 2004 to 2026). "To further characterize SMOC1 expression in colorectal lesions, we next analyzed associations between SMOC1 expression and clinicopathological characteristics in respective tumor types." (PMID 38429655, 2024). "Here, we noted a novel, tumor-unique SMOC1 isoform identified as Novel_in_Catalog by the SQANTI3 classifier supported by 1,038 long-reads." (PMID 38287261, 2024). "Top differentially suppressed genes as the tumor transformed included SMOC1, BCAN, NES, AIF1L, ENC1, and IGF2 (p < 0.01)." (PMID 39256867, 2024). "Among them, GINS3 was characterized by high tumor purity, immune-desert, activation of EGFR and ephrin receptors, chromosomal instability, fewer KRAS mutations, SMOC1 methylation, immunotherapeutic resistance, and high sensitivity to cetuximab and bevacizumab." (PMID 38429655, 2024). "SMOC1 levels are elevated in some forms of cancer, and given that the cleavage of osteopontin by thrombin initiates its tumor promoting activity, it will be interesting to determine whether or not the interaction between SMOC1 and thrombin underlies some of this tumor-promoting ability." (PMID 35626753, 2022). "GINS3, a KRAS-inactivated subtype, was featured by high tumor purity, immune-desert, activation of EGFR and ephrin receptors, CIN, fewer KRAS mutations, and SMOC1 methylation." (PMID 36345721, 2022). "To evaluate the more specific link between SMOC1 and tumor immune infiltration, we analyzed the correlations between SMOC1 and markers of various immune cells in LGG using the TIMER and GEPIA2 databases." (PMID 34869577, 2021). "After adjusting for tumor purity, the expression of SMOC1 was significantly negatively correlated with gene markers of most immune cells in LGG, especially gene markers of CD8+ T cells, T cells (general), Th2 cells, dendritic cells, TAMs, and M1 macrophages." (PMID 34869577, 2021). "In vivo, inoculation of SW480 cells transiently transfected with a SMOC1 expression vector or empty vector into nude mice revealed that SMOC1 moderately suppresses tumor formation." (PMID 29435136, 2018). "Ectopic expression of SMOC1 suppressed proliferation, colony formation and in vivo tumor formation by CRC cells." (PMID 29435136, 2018). "The expression of SMOC1 was significantly increased in tumor samples of LGG." (PMID 34869577, 2021). "Finally, we developed a gene signature (PCSK1 and SMOC1) defining the metastatic potential of the tumor and its prognostic value was validated in a cohort of thirty G1/G2 patients underwent surgical resection." (PMID 34671197, 2021). "The results showed that, regardless of the chip or protein levels, VPS28, HSF1, and PUF60 showed higher expression in tumour tissues than in normal tissues, while COL17A1 and SMOC1 showed significantly higher expression in the adjacent tissues compared with the tumour tissues." (PMID 32964046, 2020). "We assume that similar to SMOC2, SMOC1 might also be involved in tumor development." (PMID 34869577, 2021). "However, the role of SMOC1 in tumor genesis and progression is still unclear." (PMID 34869577, 2021). "Ectopic expression of SMOC1 suppressed CRC cell proliferation, suggesting its tumor suppressor function." (PMID 38429655, 2024). "However, the prognostic value and the biological function of SMOC1 in tumor remain unclear." (PMID 34869577, 2021). "We found that SMOC1 was positively correlated with tumor purity (cor = 0.347, p = 5.82e-15) in LGG but not in GBM." (PMID 34869577, 2021). "In addition, the Tumor Immune Estimation Resource and TISIDB databases were used to evaluate the correlations between SMOC1 expression and tumor-infiltrating immune cells in the tumor microenvironment." (PMID 34869577, 2021). "The expression of SMOC1 was negatively correlated with levels of infiltrating B cells, CD8+ T cells, CD4+ T cells, macrophages, neutrophils, and dendritic cells, as well as gene markers of most immune cells in the LGG tumor microenvironment." (PMID 34869577, 2021).
tumor (continued). "Additionally, we observed in our analysis that there was a positive correlation between SMOC1 expression and tumor purity in LGG, which suggested that the expression of SMOC1 was more likely from tumor cells, which was consistent with a previous study." (PMID 34869577, 2021). "The results showed that the expression of SMOC1 was remarkably increased in tumor samples of LGG, whereas there were no significant changes in GBM and LUAD samples, which was consistent with previous studies." (PMID 34869577, 2021). "Interestingly, SMOC1 expression levels did not correlate with tumor locations among SSLs, suggesting that SSLs express high levels of SMOC1 irrespective of the locations." (PMID 38429655, 2024). "Survival curves showed that both PCSK1 and SMOC1 protein expression levels were significantly correlated with the recurrence, and double-positive PCSK1/SMOC1 protein expression was the more unfavorable prognostic factor than a single marker, tumor size, and tumor grade." (PMID 34671197, 2021).